APOA1 (apolipoprotein A1)
Diseases named in the same sentence as APOA1 in open-access papers (continued):
Sharing a sentence is not in itself a finding about the gene and the disease.
Tangier disease (20 papers, 2013 to 2025). "Rare mutations of ApoA1 are associated with polyneuropathy (Tangier disease), and lipids are crucial players in inflammation." (PMID 39909798, 2025). "Deficiency of HDL-C (hypoalphalipoproteinemia) can be a result of genetic defects of ABCA1, LCAT and ApoA1, which leads to Tangier disease, Fish-eye or Familial LCAT deficiency disease, and ApoAI deficiency or ApoA1 variants." (PMID 33669729, 2021). "Increased catabolism of ApoA1 is a hallmark of the functional impairment of ABCA1 in Tangier’s disease and in liver Abca1 deficient mice." (PMID 29144234, 2017). "Hypoalphalipoproteinemia includes the following diseases: Tangier disease, Apolipoprotein A-I (APOA1) deficiency, and Lecithin cholesterol acyltransferase (LCAT) deficiency (including Familial LCAT deficiency (FLD) and Fish eye disease (FED)) (Hegele 2020 review)." (PMID 37138899, 2022). "In humans, loss of APOA1 causes familial HDL deficiency, Tangier disease, and familial visceral amyloidosis." (PMID 29066772, 2017). "A patient with Tangier disease and P. falciparum was reported to have apolipoprotein A1 levels below detection levels." (PMID 24314058, 2013). "APOA1 is one of the major components of HDL-C in plasma, defects in APOA1 gene are associated with HDL-C deficiencies, including Tangier disease." (PMID 23675527, 2013). "Functional mutations in ABCA1 cause Tangier disease, which is characterized by very low levels of plasma HDL apoA1." (PMID 23656756, 2013). "Genetic mutations in ABCA1 (Tangier disease), LCAT (familial lecithin:cholesterol acyltransferase deficiency), ApoA1 (familial apolipoprotein (Apo) A1 deficiency), and UBIAD1 (Schnyder corneal dystrophy, SCD) all result in corneal accumulation of lipids including cholesterol." (PMID 34547023, 2021). "Therefore, as in Tangier’s disease, the significant decrease in hepatic Abca1 likely accounts for the decreased plasma ApoA1 in the Lrp1Y63F mouse." (PMID 29144234, 2017). "More importantly, results from Tangier disease patients and liver-specific ABCA1-knockout mice suggest that hepatic ABCA1 is the most important source of nascent ApoA1 and is absolutely required for the maintenance of the majority of the plasma HDL pool." (PMID 27136542, 2016).
colon cancer (18 papers, 2007 to 2023). "In a large European prospective study, APOA1 was found to be negatively associated with the risk of colon cancer." (PMID 35421932, 2022). "Linoleic acid, an unsaturated fatty acid, also stimulated the secretion of apoA-1 from human colon cancer-derived Caco-2 cells by activating PPAR-gamma." (PMID 34202121, 2021). "There is one cohort study which showed the pre-diagnostic concentrations of APOA1 to be inversely associated with risk of colon cancer, but not rectal cancer." (PMID 26463353, 2016). "APOA1 expression was correlated with better prognosis of rectal cancer (p = 0.023) but not colon cancer." (PMID 35945555, 2022).
hypoalphalipoproteinemia (18 papers, 2008 to 2025). A metabolic disorder characterized by deficiency of high density (alpha) lipoprotein in the blood. "APOA1: Genetic loss-of-function variants in the APOA1 gene cause familial hypoalphalipoproteinemia in an autosomal co-dominant manner." (PMID 40004987, 2025). "The authors estimated that in the Japanese population, the frequency of hypoalphalipoproteinemia caused by APOA1 mutations is 0.3% in the general population and 6% in individuals with low plasma HDL-C levels." (PMID 37510094, 2023). "The frequency of hypoalphalipoproteinemia due to APOA1 gene mutations in the Japanese population was estimated at 0.3% in the general population and 6% of individuals with low plasma HDL-C levels." (PMID 35743896, 2022). "Compound homozygous, heterozygous, and heterozygous mutations in the APOA1 gene cause familial hypoalphalipoproteinemia (Hypoalphalipoproteinemia, Primary, 2) (OMIM, 618,463), which also includes the Combined Apo-I and apoC-III, both being autosomal recessive diseases." (PMID 35743896, 2022). "Familial hypoalphalipoproteinemia is another autosomal codominant condition that manifests as severely low HDL-C with typically normal triglycerides and LDL-C but is more commonly caused by biallelic variants in the APOA1 gene." (PMID 39691320, 2024). "Genetic mutations in ABCA1, apoA-1, and LCAT are associated with familial hypoalphalipoproteinemia." (PMID 32455724, 2020). "We evaluated targeted, next-generation sequencing data from patients with very low levels of HDL cholesterol (i.e., hypoalphalipoproteinemia) with the VarSeq-CNV® caller algorithm to screen for CNVs that disrupted the ABCA1, LCAT, or APOA1 genes." (PMID 29866657, 2018). "Bi-allelic hypoalphalipoproteinemia causes near complete absence of serum HDL-C and apoA1 that causes corneal opacities, xanthoma, and ASCVD." (PMID 40004987, 2025). "CNVs disrupting ABCA1, APOA1, or LCAT in individuals with hypoalphalipoproteinemia have not yet been reported." (PMID 29866657, 2018).
steatosis (17 papers, 2005 to 2026). Increased lipid within the cytoplasm of cells. "T2DM was also associated with lower ApoA1 (p = 0.002) in men and women with significant steatosis S2S3." (PMID 35327501, 2022). "While we have established APOA1 as a key functional regulator in OA-induced steatosis, the precise transcriptional regulatory relationship between APOA1 and downstream genes such as ACACA, FASN, CPT1, and APOB remains to be fully elucidated." (PMID 41463887, 2025). "Genes involved in steatosis (Cd36, Lpl), hepatoxicity (Avpr1a, Pla2g12a), necrosis (Serpine1), fatty acid metabolism (Acox1, Cpt1b, Cyp4a10, Ehhadh), lipid transport (Apoa1), and PPAR transcription factors (Pparδ) were altered with PFHpS exposure compared to vehicle-exposed animals." (PMID 39066581, 2024). "Besides, APOA-1 overexpression can reduce steatosis by decreasing reactive oxygen species (ROS) levels and suppressing COX-2-induced inflammation in hepatocytes." (PMID 34790226, 2021). "The high consumption of carotenoids could promote atheroprotective properties, since the overexpression of APOA1 could improve the reverse cholesterol transport, decreasing the cholesterol content in the liver and improving the hallmarks of the steatosis and then the progression of NAFLD." (PMID 33114278, 2020). "The heatmap showed that the B4 cluster expressed a series of lipid-metabolism-associated genes, such as APOA1, APOA2, and APOA3, and UMAP plotting also showed that B4 cells highly expressed APOC1 and APOE, implying that the B4 cluster may be associated with steatosis in the ALC group." (PMID 36817578, 2023). "The lower expression of APOB could contribute to the steatosis in Pi*ZZ AATD patients, as it has been similarly described for APOA1 and APOF in NAFLD." (PMID 37569847, 2023). "ApoA1 is highly associated with HDL-cholesterol and a negative association was also expected with steatosis." (PMID 16375767, 2005). "ST has higher AUROC, 0.80 (0.02) than all the isolated components for the diagnosis of steatosis grade 2–4: ALT, GGT, triglycerides 0.63 (0.02), BMI 0.61 (0.02), glucose 0.61 (0.02), bilirubin 0.60 (0.02), ApoA1 0.56 (0.02), A2M 0.56 (0.02) and cholesterol 0.53 (0.02) – all P values < 0.03." (PMID 16375767, 2005).
asthma (16 papers, 2012 to 2024). "The main structural protein of HDL-cholesterol, apolipoprotein A1 is associated with a favorable development of asthma." (PMID 38999820, 2024). "ApoA-1 has recently been identified as a potential new therapeutic target for airway inflammation in asthma." (PMID 22970180, 2012). "Endogenous ApoA-1 negatively controls the OVA-treated neutrophilic airway inflammation in asthma." (PMID 29086354, 2018).
autoimmune disease (16 papers, 2010 to 2024). A disorder resulting from loss of function or tissue destruction of an organ or multiple organs, arising from humoral or cellular immune responses of the individual to their own tissue constituents. "Anti-apoA-1 IgG levels (a) independently predict all-cause mortality in the general population and (b) are linked to FCRL3, a susceptibility gene for numerous autoimmune diseases." (PMID 28458671, 2017). "Steroid use has been shown to increase LDL and HDL, as well as apoA1 levels in patients with autoimmune disease, and short-term steroid use may increase the levels of lecithin cholesterol acetyl transferase (LCAT) and increase levels of HDL2." (PMID 37372137, 2023). "Furthermore, previous studies have proposed that APOA1 functions as an immune regulator, capable of suppressing pro-inflammatory cytokines produced by activated T cells in specific autoimmune diseases." (PMID 38143756, 2023). "In this large population based study anti-apoA-1 IgG levels independently predicted all-cause mortality and were found to be linked to FCRL3, a susceptibility gene for numerous autoimmune diseases, which encodes a member of the immunoglobulin receptor superfamily." (PMID 29423541, 2018). "The vast majority of our patient cohort had received prior IFN-based anti-viral therapy and IFN may induce autoimmune disorders or worsen pre-existing autoimmune disorders, so it will be important to establish whether the prevalence of anti-apoA-1 IgG is similar in untreated HCV infection." (PMID 29423541, 2018). "Previous studies using the same ELISA to detect serum anti-apoA-1 IgG have found it in a proportion of healthy subjects (0–6.5%) without CVD or autoimmune disease." (PMID 29423541, 2018). "The decrease in APOA1 and the increase in SAA showed specifically in NPSLE in this study may be related to the inflammatory state that is characteristic of an autoimmune disease like SLE." (PMID 30584474, 2018).
colitis (16 papers, 2017 to 2025). Inflammation of the colon. "TfebΔIEC mice exhibited lower levels of lipoprotein ApoA1 expression, which is downregulated in Crohn’s disease patients and causally linked to colitis susceptibility." (PMID 29066772, 2017). "Impact of HFD on DSS‐induced colitis may be linked to intestinal dysbiosis and specific genes such as Abca8b, Ace2, Apoa1, Apoa4, Apoc3, Aspa, Dpp4, Maob, Slc34a2, Slc7a9, and Trpm6." (PMID 39479684, 2024). "Overall, the findings indicate that the impact of HFD on DSS‐induced colitis may be linked to intestinal dysbiosis and specific genes such as Abca8b, Ace2, Apoa1, Apoa4, Apoc3, Aspa, Dpp4, Maob, Slc34a2, Slc7a9, and Trpm6." (PMID 39479684, 2024). "Indeed, TFEB depletion increases the susceptibility of enterocytes to injury and consequent colitis by downregulating apolipoprotein A1 (ApoA1) in a manner reminiscent of Crohn's disease." (PMID 37728021, 2023). "Moreover, ApoA1 knockout in a rodent model of colitis-induced colorectal carcinogenesis was associated to exacerbated pathological and inflammatory features and also to higher proliferative index." (PMID 30745873, 2018). "The loss of APOA1 expression that we observed in unperturbed TfebΔIEC mice could explain, at least partially, their enhanced susceptibility to epithelial injury and colitis." (PMID 29066772, 2017). "Furthermore, loss of intestinal ApoA1 results in greatly enhanced susceptibility to DSS-induced colitis and malignant transformation in mice." (PMID 29066772, 2017). "Such defects in APOA1 expression could provide a mechanistic basis for the greatly enhanced susceptibility of TfebΔIEC animals to chemically-induced colitis." (PMID 29066772, 2017). "After recovery from DSS colitis, while Tfebflox/flox animals exhibited reduced but detectable APOA1 expression, APOA1 expression in TfebΔIEC animals was lost." (PMID 29066772, 2017). "The comparison results showed that the levels of low-density lipoprotein cholesterol (LDL-C), high-density lipoprotein cholesterol (HDL-C), apolipoprotein A1 (ApoA1), Apo E and total cholesterol (TC) in distal colitis were significantly higher than extensive colitis." (PMID 37457023, 2023). "Thus, we document a novel role for TFEB in the expression of APOA1, a known protective factor against epithelial injury and colitis in rodents and humans." (PMID 29066772, 2017).
depression (16 papers, 2015 to 2025). "A previous meta-analysis established a significant association between low APOA1 expression and an increased incidence of depression." (PMID 39654644, 2024). "Another study of electroconvulsive therapy in specific groups of patients with depression demonstrated, from a lateral perspective, that improvement in depressive behavior is associated with an increase in APOA1, a major component of HDL cholesterol." (PMID 37469359, 2023). "A large-scale meta-analysis found that lower levels of ApoA1 were associated with increased odds of depression." (PMID 35479414, 2022). "Thus, it is highly possible that the pathophysiology of depression may be closely associated with changes in circulating ApoA1 levels." (PMID 35479414, 2022). "Overall, HDL-C reduction in depression reflects a multifactorial pathology involving LCAT/apoA1/PON1 dysfunction, cortisol-driven lipid dysregulation, and pro-inflammatory HDL remodeling." (PMID 40511456, 2025). "The analysis of receiver-operating characteristic (ROC) curve disclosed that the changes in plasma ApoA1 levels were able to serve as a biomarker for depression in MDD patients." (PMID 35479414, 2022). "For clinical practice, the following specific recommendations are provided: Clinicians are recommended to perform a four-component lipid profile (total cholesterol, triglycerides, LDL-C, HDL-C) and apolipoprotein A1/B testing in patients with depression during their first visit." (PMID 41450840, 2025). "Finally, the clinical depression score BDI-II showed a positive correlation with the apolipoprotein ratio ApoB100/ApoA1 (r = 0.20, P < 0.01)." (PMID 40404791, 2025). "Fasting glucose, overweight, hip circumference, depression, insomnia, and sleep apnea showed no genetic association with changes in the ApoB/ApoA1 ratio." (PMID 38310324, 2024). "Moreover, an electroshock regimen targeting specific types of depression demonstrated that improvements in depressive behavior were correlated with increased APOA1 levels." (PMID 39654644, 2024). "Collectively, these results indicate that c-MSST mice may exhibit resistance to stress-induced development of depression-like behaviors via regulation of proteins positioned in ApoA1." (PMID 35479414, 2022). "Importantly, the changes in plasma ApoA1 levels were able to predict the response to rTMS treatment in MDD patients, further supporting the potential of ApoA1 as a biomarker for depression." (PMID 35479414, 2022). "Concurrently, decreased apoA1 and PON1 levels in depression compromise HDL’s anti-inflammatory capacity, allowing IL-6-driven neuroinflammation to persist." (PMID 40511456, 2025). "Alpha 1-antitrypsin (AAT) and apolipoprotein A1 (APOA1) were closely related with inflammatory response; both were found to be significantly decreased in major depressive disorder (MDD) patients." (PMID 35372107, 2022). "Among there differential variables, 14 differential OTUs (mainly belonging to Firmicutes) and five differential inflammation-related factors (APN, APOA1, AAT, NEUT% and BASO) were found to be significantly correlated to the depression severity." (PMID 35372107, 2022). "Collectively, these results imply that ABCA1/ApoA1 signaling pathway in the V1 is selectively activated by c-MSST, thereby rendering resistance to depression-like behaviors and synaptic dysfunction in mice." (PMID 35479414, 2022). "Out of our 26-analyte panel, only three proteins (ApoH, ApoA1 and B2M) were altered in bipolar disorder patients and four (MIF, ACE, TNC and ILra) were changed in patients with depression." (PMID 26171982, 2015). "The aim of the study was to explore the relationship between cutaneous pain thresholds, Zung Self-Rating Depression Scale (ZUNG-D) scores, Leeds Dependence Questionnaire (LDQ) scores and serum levels of apolipoprotein A1 (APOA1) and apolipoprotein E (APOE) in patients with MOH." (PMID 30238173, 2018).
depression (continued). "Furthermore, we observed a negative correlation between ApoA1 levels and the scores of 24-item Hamilton Depression Rating Scale (HAMD-24)." (PMID 35479414, 2022). "This study suggests that apolipoprotein A1 levels are lower and cold manifestations are more common in PSF patients without depression than in those without fatigue." (PMID 34942944, 2021).
liver disease (16 papers, 2014 to 2025). "The decrease in apolipoprotein-A1 in 2020 compared to 2019, and 2018 cannot be explained by bias due to gender, age, the cause of liver disease, or the severity of liver diseases." (PMID 33216772, 2020). "ApoB/ApoA1 ratio in the serum of individuals with various forms of liver diseases and healthy people varied." (PMID 38744926, 2024). "Our previous cohorts of patients with severe liver diseases allowed us to identify the major risks of a significant decrease in apolipoprotein-A1 (false positives), mainly due to severe hepatic insufficiency and severe fibrosis." (PMID 33216772, 2020). "ApoA1 and haptoglobin have been applied in the current test system for liver disease." (PMID 29179490, 2017).
melanoma (16 papers, 2013 to 2022). A malignant, usually aggressive tumor composed of atypical, neoplastic melanocytes. "Zamanian-Daryoush’s study on the murine malignant melanoma model revealed that, compared to apoA1-deficient mice, human apoA1 transgene mice exhibited reduced tumor burden, decreased metastasis, and enhanced survival, which was associated with the increased infiltration of M1 macrophages." (PMID 36585674, 2022). "In a panel of 60 diverse human cancer cell lines (NCI-60) used by the Developmental Therapeutics Program of the US National Cancer Institute, we also found that both APOA1 and APOE mRNA levels were low, with the exception, for apoE only, of the T-47D cell line and melanoma cell lines." (PMID 32321558, 2020).
nasopharyngeal carcinoma (15 papers, 2015 to 2025). A carcinoma arising from the nasopharyngeal epithelium. "Research on nasopharyngeal carcinoma has shown that serum ApoA1 level higher than 1.025 g/L is an independent predictor of longer overall survival, less local recurrence or distant metastasis in patients." (PMID 35100989, 2022). "It has been also suggested that serum ApoA1 correlated with the survival rate of patients suffering from different types of tumors, such as gastric cancer, nasopharyngeal cancer, and colorectal cancer." (PMID 35100989, 2022). "The aim of this study was to investigate the correlation between ApoB/ApoA1 ratio and the severity of radiation‐induced brain necrosis (RN) in patients who underwent radiotherapy after nasopharyngeal carcinoma (NPC)." (PMID 32017458, 2020). "Additionally, pretreatment levels of ApoA1 are predicting favorable outcomes in patients undergoing anti-PD1 therapy for metastatic colorectal cancer, intrahepatic cholangiocarcinoma, and nasopharyngeal carcinoma." (PMID 40821786, 2025).
endotoxemia (14 papers, 2010 to 2023). "A small but statistically significant association with endotoxemia was observed for apoA1, whereas the associations for apoB and apoB/apoA1-ratio were considerably stronger." (PMID 33243051, 2021). "Administration of naked ApoA1 purified from human plasma has shown to have some beneficial effects in both rat and mouse LPS-induced endotoxemia models." (PMID 26557091, 2015). "Made from purified human ApoA1 and soybean phosphatidylcholine (PC) at a molar ratio of 1:2 protein to lipid, CSL-111 has repeatedly shown efficacy in reducing the burden of LPS-induced endotoxemia both in vitro and in vivo in rabbit and human models." (PMID 26557091, 2015).